IP6K1 (inositol hexakisphosphate kinase 1)
Diseases named in the same sentence as IP6K1 in open-access papers (continued):
Sharing a sentence is not in itself a finding about the gene and the disease.
male infertility (2 papers, 2018 to 2024). The inability of the male to effect fertilization of an ovum after a specified period of unprotected intercourse. "IP6K1 can be considered a predictable marker for male infertility since the knockout of IP6K1 affects several steps of sperm development." (PMID 38403246, 2024). "Disruption of endocytosis in EHD4 KO mice results in male infertility similar to that of IP6K1 KO mice." (PMID 29728588, 2018). "It is uncertain whether the male infertility in IP6K1 KOs is dependent on 5-IP7 or IP8, both products of IP6K1." (PMID 29728588, 2018). "Thus IP6K1 may be a marker for male infertility with prognostic value." (PMID 29728588, 2018).
mental disorder (2 papers, 2024 to 2025). A disease that has its basis in the disruption of mental process. "Although it is not fully understood whether the inhibition of ISYNA1 by IP6K1 is mediated by 5-IP7, the enzyme has been linked to psychiatric disorders such as BD." (PMID 40001529, 2025). "This suggests that targeting the IP6K1–GSK3β interaction could offer therapeutic benefits for BD and other psychiatric disorders involving GSK3 dysregulation." (PMID 40001529, 2025). "Consistent with the vital roles played by IPs, IP synthesizing enzymes such as IP6K1, IP6K2, IP6K3, and IPK2 are highly expressed in neuronal cells, suggesting that they play crucial roles in neurons and, by extension, neurodegenerative and psychiatric diseases." (PMID 40001529, 2025).
schizophrenia (2 papers, 2020 to 2025). A major psychotic disorder characterized by abnormalities in the perception or expression of reality. "Our findings that IP6K1, as a physiological player, regulates behavior highlight the significance of inositol pyrophosphate metabolism in the brain and provide insights into the treatment and management of psychiatric diseases such as schizophrenia." (PMID 32381051, 2020). "We performed behavioral analyses to determine whether IP6K1-KO mice show any changes in sensorimotor gating, one of the well-known characteristics of schizophrenia." (PMID 32381051, 2020). "Moreover, it will be interesting to determine how IP6K1/IP7 mediates synaptic vesicle trafficking in neurons, and this may address the dysregulation of synaptic vesicle cycling in schizophrenia." (PMID 40001529, 2025).
atherosclerosis (1 paper, 2024). A disease characterized by the build-up of fatty material and calcium deposition in the arterial wall resulting in partial or complete occlusion of the arterial lumen. "Our study demonstrates that depleting 5PP-InsP5 by inhibiting IP6K1 is an effective approach to enhance the production of apoA-I and consequently lowers the rate of atherosclerosis." (PMID 39643078, 2024). "Hepatocyte-specific deletion of IP6K1 elevates circulating apoA-I levels, which augments cholesterol efflux and lowers the burden of atherosclerosis." (PMID 39643078, 2024). "There is a possibility that atherosclerosis in the setting of apoA-I-deletion is too severe to observe an improvement with IP6K1 deletion, although the in vivo study suggests that apoA-I is the mediator." (PMID 39643078, 2024). "Hepatocyte-specific deletion of IP6K1 elevates circulating apoA-I, leading to enhanced cholesterol efflux and reduced burden of atherosclerosis." (PMID 39643078, 2024). "The effects of IP6K1 inhibition on atherosclerosis in females require a comprehensive study." (PMID 39643078, 2024). "In this study, we found that deletion of IP6K1 attenuates atherosclerosis." (PMID 39643078, 2024). "In this study, we demonstrate that genetic deletion or pharmacological inhibition of IP6K1 in hepatocytes upregulates apoA-I, a major structural and functional protein of HDL, augmenting cholesterol efflux, and attenuating atherosclerosis." (PMID 39643078, 2024). "In contrast, deletion of IP6K1 in hepatocytes enhances apoA-I production by preventing UBE4A-mediated apoA-I degradation, and subsequent attenuates atherosclerosis." (PMID 39643078, 2024). "Deletion of IP6K1 in the apoA-I null mice failed to augment cholesterol efflux, and did not alleviate atherosclerosis, confirming that the atheroprotective effects of hepatocyte-specific IP6K1 deletion require apoA-I." (PMID 39643078, 2024).
breast carcinoma (1 paper, 2019). "Note that IP6K1 was not in the list of highly correlated genes in the all four categories of breast cancer, because its correlation coefficient with BAP1 in the black-alive category was 0.73, which was less than the threshold 0.8." (PMID 30716094, 2019).
chronic obstructive pulmonary disease (1 paper, 2020). A chronic and progressive lung disorder characterized by the loss of elasticity of the bronchial tree and the air sacs, destruction of the air sacs wall, thickening of the bronchial wall, and mucous accumulation in the bronchial tree. "Neutrophils from IP6K1 KO mice accumulate in the lungs and probably contribute to chronic obstructive pulmonary disease (COPD), while when stimulated with IP6K1, IP7-mediated Akt inhibition enables neutrophil death and protects against COPD." (PMID 32992691, 2020).
cognitive decline (1 paper, 2022). "Mapping of GWAS results identified genes that have been previously associated with cognitive decline including STAU1, SEMF3A, IP6K1, MST1, the ATNX2/BRAP locus, ALDH2 and DDX27, where a likely functional missense variant is highly associated." (PMID 35052462, 2022).
colorectal adenocarcinoma (1 paper, 2022). The most common type of colorectal carcinoma. "We showed that the depletion of host IP6K1 markedly potentiated the growth of MC38 colorectal adenocarcinoma cells." (PMID 35308129, 2022).
sarcopenia (1 paper, 2019). Progressive decline in muscle mass due to aging which results in decreased functional capacity of muscles. "The mTORC1 regulators TSC were also phosphorylated in IGF-1 treated -/-inositol cell lines compared to control which suggests IP6K1 could be implicated in Akt-mTORC1 signaling and therefore sarcopenia." (PMID 31552262, 2019). "Taken together, it is hypothesized that IP6K1 may have a role in the onset of sarcopenia, and this review aims to discuss the possible role it has in anabolic resistance in aging skeletal muscle." (PMID 31552262, 2019).
squamous cell carcinoma (1 paper, 2016). A carcinoma arising from squamous epithelial cells. "To determine if the reduced invasion potential of IP6K1 depleted cancer cells extends to Ip6k1 knockout cells in vivo we utilized the 4-nitroquinoline 1-oxide (4NQO) oral squamous cell carcinoma model." (PMID 27140681, 2016).
cancer (7 papers, 2016 to 2025). A tumor composed of atypical neoplastic, often pleomorphic cells that invade other tissues. "When IP6K1 is depleted in mouse embryonic fibroblasts and cancer cells, they undergo cellular changes associated with decreased cell migration and dysregulated focal adhesion kinase (FAK) activity." (PMID 35308129, 2022). "IP6K1 has been implicated in biological processes, such as energy metabolism, insulin signaling, trafficking, chromatin remodeling, cell migration, cancer metastasis, and neutrophil functions." (PMID 32992691, 2020). "Cancer cells deficient in IP6K1 show decreased anchorage independent growth, migration and invasion." (PMID 27140681, 2016). "Although several genes at the IP6K1 locus (p = 6.57 × 10−9) have been linked to various cancers, the causal gene is unknown." (PMID 40495383, 2025). "Collectively, these data suggest a major contribution of host IP6K1 to the immune control of cancer cell growth in the tumor microenvironment." (PMID 35308129, 2022). "Future studies using various types of cancer cells as well as other IP kinase mouse models will be required to fully elucidate complex cell type-specific functions of host IP6K1 in modulating immune responses among tumor cells and their microenvironment." (PMID 35308129, 2022). "Recent studies revealed key actions of IP6K1 in the control of tumorigenesis and cancer progression." (PMID 35308129, 2022). "When IP6K1 is depleted in mouse embryonic fibroblasts and cancer cells, such as HeLa and HCT116, they undergo morphological changes that are associated with decreased cell migration." (PMID 32397291, 2020). "Taken together, these data indicate that IP6K1 is a physiological determinant of cancer cell migration." (PMID 32397291, 2020). "Cancer cells with lower IP6K1 levels display reduced migration, invasion, and anchorage-independent growth." (PMID 27140681, 2016). "Together, our data show that the depletion of IP6K1 lowers chemotactic and collective migration in these cancer cell lines." (PMID 27140681, 2016). "Not much is known about the functions of the equally abundant and ubiquitously expressed IP6K1 isoform in cell migration, invasion and cancer progression." (PMID 27140681, 2016). "Modulating the levels and activity of IP6K1 through therapeutic drugs may help in improving immunity and controlling cancer spread, instilling hope for immune compromised and cancer patients." (PMID 38403246, 2024). "While targeting IP6K1 in various cancer cells has been well reported to control cancer cell motility and invasiveness, the role of host IP6K1 in tumor progression remains unknown." (PMID 35308129, 2022). "Therefore, further research is required to fully explore the impact of IP6K1 on the cellular characteristics of cancer in vivo." (PMID 32397291, 2020). "We therefore sought to determine the role IP6K1 has on the tumorigenic properties of cancer cells." (PMID 27140681, 2016). "Thus, our data reveal that like IP6K2, IP6K1 is also involved in early cytoskeleton remodeling events during cancer progression." (PMID 27140681, 2016). "Therefore, our data shows that IP6K1 expression is required for cancer cells to achieve their complete oncogenic potential." (PMID 27140681, 2016). "In conclusion, we demonstrate that host IP6K1 acts as a tumor suppressor, most likely by fine-tuning diverse tumor-immune cell interactions, which might have implications for improving the host response against cancer progression." (PMID 35308129, 2022). "Previous studies also proposed IP6K1 and 5-IP7 in the control of cellular migration from specific cell types such as neutrophils as well as cancer." (PMID 35308129, 2022). "Here, we summarize the current understanding that established IP6K1 and the other IP6K isoforms as possible targets for cancer therapy." (PMID 32992691, 2020). "As observed in IP6K1-KO models, IP6K2-KO, too, reduces cell–cell adhesion, growth, spreading, metastasis, and FAK phosphorylation in cancer cells." (PMID 32992691, 2020).
cancer (continued). "Unfortunately, the role of IP6K1 in cancer motility and invasiveness has received little or no attention, despite the fact that some reports have identified it as a target for reducing migration and invasion in several types of cancer." (PMID 32992691, 2020). "Our study therefore uncovers similarities and differences in the roles of IP6K1 and IP6K2 in cancer progression, and we propose that an isoform-specific IP6K1 inhibitor may provide a novel route to suppress carcinogenesis." (PMID 27140681, 2016). "Together, these data suggest that IP6K1 may not play a role in tumor initiation, but is required for aggressiveness of cancer cells by regulating anchorage independence, cell migration and invasion." (PMID 27140681, 2016).
metabolic disease (7 papers, 2020 to 2025). A congenital disorder (due to inherited enzyme abnormality) or acquired (due to failure of a metabolically important organ) disorder resulting from an abnormal metabolic process. "Modulating the activity of mammalian IP6 kinases, especially IP6K1, has been proposed as a potential therapeutic target for managing metabolic diseases, mostly based on preliminary results on mice models." (PMID 38397389, 2024). "How does IP6K1 mediated enhancement in insulin secretion and inhibition in insulin signaling fit in the context of metabolic diseases?" (PMID 32204420, 2020). "BBB- and BTB-impermeable IP6K1 (or IP6K1+IP6K3) selective inhibitors are desirable for the treatment of metabolic diseases." (PMID 32204420, 2020). "Hence, the anabolic functions of IP6K1 can be targeted in metabolic diseases in the mid-late stage of life." (PMID 32204420, 2020). "Besides, deletion of IP6K1 increases insulin sensitivity, and alleviates hepatic metabolic dysfunction, indicating that IP6K1 may be a potential treatment target for metabolic diseases." (PMID 39643078, 2024).
tumor (3 papers, 2016 to 2024). "To explore the biology underlying the increased tumor burden in IP6K1 KO mice, we examined indicators of proliferation and angiogenesis." (PMID 35308129, 2022). "Further studies in different animal models are needed to elucidate the complex roles of IP6K1 in different host cells as an immune modulator and/or tumor suppressor." (PMID 38403246, 2024). "In IP6K1 knockout mice, tumor cell growth was noticeably accelerated, and host survival was drastically reduced compared with wildtype mice." (PMID 38403246, 2024). "In this manner, host IP6K1 acts as a tumor suppressor by fine-tuning various tumor-immune cell interactions." (PMID 38403246, 2024). "A marked reduction of the CD80+ IFN-γ M1 macrophages was further noted in the same tumor tissues from IP6K1 KO mice." (PMID 35308129, 2022). "FACS analyses revealed i) increased CD11b+Gr1 + IL10+ myeloid cells, ii) decreased anti-tumor, M1 TAMs, and iii) markedly reduced infiltration of dendritic cells into the tumor microenvironment in IP6K1 KO mice." (PMID 35308129, 2022). "Accordingly, we found that mean survival time was significantly decreased in tumor-bearing IP6K1 KO animals, compared to WT mice." (PMID 35308129, 2022). "Flow cytometry analysis revealed increased total viable CD45.2+ immune cells in tumors grown from IP6K1 KO mice, suggesting more tumor-infiltrating immune cells in the IP6K1 KO tumor microenvironment." (PMID 35308129, 2022). "Accordingly, we analyzed T cell populations and observed decreased amounts of CD8+ T cells in tumors grown in IP6K1 KO mice, relative to control tumor tissues." (PMID 35308129, 2022). "Bodyweight became significantly increased in IP6K1 KO mice after day 27 post-tumor inoculation, which reflects the higher tumor mass in IP6K1 KO mice compared to control." (PMID 35308129, 2022). "Further analyses will be needed to dissect the contribution of IP6K1 to the control of dendritic cell functions in the tumor tissues by using the conditional deletion of IP6K1 in dendritic cells." (PMID 35308129, 2022). "To further dissect changes in leukocyte populations, we next analyzed tumor-associated macrophages (TAMs) and identified significantly decreased CD80+ M1-polarized macrophages from tumor tissues in IP6K1 KO mice." (PMID 35308129, 2022). "On the other hand, knocking out IP6K1 in mice weakened the immunity and accelerated tumor growth." (PMID 38403246, 2024). "The unknown facets of IP6K1 in spermatogenesis, its role in O-GlcNAcylation of hepatic proteins, and its roles as an immune modulator/tumor suppressor in diverse host cells necessitate focused studies." (PMID 38403246, 2024). "Therefore, reduced detection of total and CD8+ killer T cell population in the tumor tissue from IP6K1 KO mice appears the consequence of defective IP6K1 KO dendritic cells." (PMID 35308129, 2022). "Since M1 macrophages can suppress tumor growth by directly killing tumor cells or indirectly controlling Th1 cell activities, diminished M1 TAMs found in tumors from IP6K1 KO conditions could contribute to the accelerated tumor growth." (PMID 35308129, 2022). "Both Akt and Erk phosphorylation levels were also unchanged in tumor tissues from IP6K1 KO mice." (PMID 35308129, 2022). "Marked reduction of IP6K1 KO dendritic cells in the tumor microenvironment may reflect complex molecular and cellular actions in vivo conditions but not in oversimplified in vitro culture settings." (PMID 35308129, 2022). "Therefore, we describe the previously unidentified role of host IP6K1 in vivo as a tumor suppressor." (PMID 35308129, 2022). "Collectively, these findings indicate that host IP6K1 deletion leads to failure of dendritic cell migration into the tumor microenvironment, thereby limiting activation and infiltration of anti-tumor CD8+ T cells, subsequently aiding tumor growth in IP6K1 KO mice." (PMID 35308129, 2022).